SMYD2 (SET and MYND domain containing 2)
Diseases named in the same sentence as SMYD2 in open-access papers (continued):
Sharing a sentence is not in itself a finding about the gene and the disease.
lung adenocarcinoma (8 papers, 2016 to 2025). A carcinoma that arises from the lung and is characterized by the presence of malignant glandular epithelial cells. "SMYD2 expression was found to be highly upregulated in lung adenocarcinoma, and high SMYD2 expression was linked to shorter overall and disease-free survival." (PMID 35498536, 2022). "Comparative analysis of paired tumor and para-carcinoma tissues showed SMYD2 overexpression across most cancer types, except for lung adenocarcinoma." (PMID 40777131, 2025). "At the same time, we analyzed the mutation rates of H3K36 enzymes (including NSD1, NSD2, NSD3, ASH1L, SMYD2, SETDB2, SETD3, and SETMAR) in lung adenocarcinoma, which showed that the amplification mutation frequency of H3K36 enzymes was at a low level." (PMID 39119928, 2024). "The prognostic value of SMYD2 expression in lung adenocarcinoma (LUAD) was determined through bioinformatics analysis, reverse-transcription polymerase chain reaction, western blotting, and immunohistochemistry." (PMID 33935284, 2021). "Endogenous methylation of MAPKAPK3 at K355 was observed in human SW1990 PDAC cells as well as human H358 and H441 lung adenocarcinoma cells, and this signal decreased upon RNAi-mediated depletion of SMYD2." (PMID 26988419, 2016). "Thus, inhibiting SMYD2 likely impacts on multiple pathways that are important for Ras-driven pancreatic cancer and lung adenocarcinoma." (PMID 26988419, 2016). "SMYD2 regulates the occurrence and metastasis of RPS7-mediated lung adenocarcinoma, representing itself as a potential prognostic biomarker and therapeutic target." (PMID 36816359, 2023). "SMYD2 could activate the transcription of PRS7 by binding to its promoter and promote tumorigenesis and metastasis in lung adenocarcinoma." (PMID 40777131, 2025). "Although several studies have reported the role and function of SMYD2 in numerous tumors, its involvement in lung adenocarcinoma (LUAD) progression has not yet been defined." (PMID 33935284, 2021). "Since they target different substrates, it is unlikely that these two distinct enzymes would compensate for each other, but the dual inactivation of SMYD2 and SMYD3 may inhibit PDAC (and lung adenocarcinoma) more potently than the inactivation of each enzyme alone." (PMID 26988419, 2016).
prostate carcinoma (8 papers, 2016 to 2025). A carcinoma that arises from epithelial cells of the prostate gland. "Similarly, SMYD2 is overexpressed in prostate cancer, and high SMYD2 expression is associated with poor prognosis." (PMID 39482529, 2024). "Daily 10 mg/kg oral OC treatments inhibited the metastatic castration-resistant prostate cancer progression and recurrence via direct SMYD2 inhibition, and suppressed its expression level." (PMID 39940255, 2025). "This study team validated the c-MET receptor tyrosine kinase (RTK) and the lysine methyl transferase SMYD2 as unique molecular targets for OC in breast and prostate cancers, respectively." (PMID 39940255, 2025). "In prostate cancer, OC’s SMYD2 inhibition can destabilize AR, potentially enhancing AR antagonists, PARP inhibitors, and taxanes." (PMID 40564985, 2025). "OC’s ability to inhibit SMYD2 has significant implications for prostate cancer treatment, particularly in disrupting the methylation of the androgen receptor (AR) at lysine residues 6–42." (PMID 40564985, 2025). "SMYD2 knockdown in prostate cancer cell lines suppresses proliferation via positive regulation of c-Myc expression." (PMID 39482529, 2024). "More recently, SMYD2 was reported as a novel molecular target in metastatic castration-resistant prostate cancer." (PMID 36838987, 2023). "OC treatments reduced SMYD2 downstream substrates, which are critical for prostate cancer growth and relapse." (PMID 35884603, 2022). "Interestingly, oleocanthal inhibits the upstream signalling of mTOR and MAPK, particularly targeting SMYD2, which plays a crucial role in prostate cancer proliferation and recurrence." (PMID 39203892, 2024). "SMYD2 overexpression in prostate cancer regulates AR protein stability through the nonhistone methylation of this protein." (PMID 39482529, 2024).
colon carcinoma (6 papers, 2015 to 2023). "Along the same line, SMYD2 deficiency in colon tumors showed increased cell death and restricted tumor growth." (PMID 35022391, 2022). "SMYD2 deficiency in colonic tumor cells strongly decreased tumor growth in two independent experimental cancer models." (PMID 35022391, 2022). "We, therefore, assessed the effects of SMYD2 deficiency on colon tumor cell proliferation." (PMID 35022391, 2022). "Based on these data together with the elevated cleaved-caspase 3 positivity in SMYD2 deficient tumors, we hypothesized that SMYD2 deficiency sensitizes colon tumor cells to TNF-induced apoptotic cell death." (PMID 35022391, 2022). "Taken together, we identified SMYD2 as an important molecule for colon tumor growth via regulating TNF-induced apoptosis and necroptosis." (PMID 35022391, 2022). "Increased expression levels of SMYD2 were detected in human and murine colon tumor tissues compared to tumor-free tissues." (PMID 35022391, 2022). "Collectively, our data show that SMYD2 is crucial for colon tumor growth and inhibits TNF-induced apoptosis and necroptosis." (PMID 35022391, 2022). "Taken together, our data indicated that SMYD2 inhibition via AZ505 administration suppresses colon tumor growth." (PMID 35022391, 2022). "In summary, our results demonstrate that pharmacological inhibition of SMYD2 suppresses colon tumor growth." (PMID 35022391, 2022). "SMYD2-regulated cell proliferation is amongst these mechanisms that was reported in various types of cancers, for instance, colon cancer." (PMID 35022391, 2022). "When we treated two HCC cells and two colon cancer cells with siRNA for SMYD2 (siSMYD2), significant downregulation of both CCND1 and cMYC was observed in concordance with the decrease of nuclear β-catenin in all of these four cell lines." (PMID 28915556, 2017). "Finally, in a translational approach, pharmacological inhibition of SMYD2 attenuated colonic tumor growth." (PMID 35022391, 2022). "In summary, our study uncovered a novel role of SMYD2 in supporting colon tumor growth." (PMID 35022391, 2022). "SMYD2 in colon tumor cells inhibits TNF-induced apoptosis and necroptosis." (PMID 35022391, 2022). "Here we discovered that SMYD2 deficiency in human or murine colon tumor cells compromised tumor growth in orthotopic and non-orthotopic CRC models." (PMID 35022391, 2022). "In summary, our results, from orthotopic and non-orthotopic transplantation of MC-38 WT and Smyd2 deficient cells, suggesting an important role of SMYD2 in murine colon tumor growth." (PMID 35022391, 2022). "Indeed, our data support the findings and indicate that SMYD2 is dispensable for cell proliferation in colon tumor cells, as we detected similar levels of proliferation." (PMID 35022391, 2022). "Here, we identified SMYD2 as a key molecule in promoting colon tumor growth." (PMID 35022391, 2022). "On a molecular level, SMYD2 deficiency sensitized colonic tumor cells to TNF-induced apoptosis and necroptosis without affecting cell proliferation." (PMID 35022391, 2022). "Some studies have shown that SET and MYND domain-containing protein 2 (SMYD2) targets RIPK1 and limits TNF-induced apoptosis and necroptosis to support colon tumor growth." (PMID 37238692, 2023). "The present study demonstrates for the first time that SMYD2 specifically regulates TNF-induced apoptosis and necroptosis in colon tumor cells." (PMID 35022391, 2022). "Increased levels of SMYD2 upregulate MDR1/P-glycoprotein expression via the MEK/ERK/AP-1 pathway in colon cancer, which promotes oxaliplatin resistance in colon cancer." (PMID 34201935, 2021). "Finally, we proved that the pharmacological inhibition of SMYD2 using two different SMYD2 inhibitors, AZ505 and BAY-598, attenuates colon tumor growth." (PMID 35022391, 2022).
colon carcinoma (continued). "To exclude the possibility of off-target effects of AZ505 or murine cell specific effects, we used BAY-598, an alternative SMYD2 inhibitor that has a different binding mode compared to AZ505, to further investigate the impact of SMYD2 inhibition in human colon tumor growth." (PMID 35022391, 2022). "Furthermore, another commercially available SMYD2 inhibitor, BAY-598, also showed similar effects, suggesting that SMYD2 inhibitors may become promising candidates for colon cancer treatment." (PMID 35022391, 2022).
cyst (6 papers, 2019 to 2026). A sac-like closed membranous structure that may be empty or contain fluid or amorphous material. "Two positive feedback loops that integrate renal inflammation in cyst development were established: SMYD2/IL-6/STAT3/SMYD2 and SMYD2/TNF-α/NF-κB/SMYD2." (PMID 41431718, 2026). "In Pkd1fl/fl:Smyd2+/+:Ksp-Cre neonates, apoptosis was rare in kidneys and knockout of Smyd2 induced cyst-lining epithelial cell death in kidneys from Pkd1fl/fl:Smyd2fl/fl:Ksp-Cre neonates." (PMID 35847973, 2022). "The research most relevant to kidney disease has shown that SMYD2 promotes cyst growth in autosomal-dominant polycystic kidney disease." (PMID 31754403, 2019). "In addition, we found that SMYD2 promotes cyst growth in ADPKD via the methylation of H3K4 and H3K36." (PMID 35847973, 2022). "Recently, our group found that the histone/lysine methyl transferase SMYD2, one of the SET and MYND-containing lysine methyl transferases (SMYD), contributed to cyst growth in ADPKD." (PMID 35847973, 2022). "We proposed that SMYD2, via two positive feedback loops: SMYD2/STAT3/SMYD2 and SMYD2/NF-κB/SMYD2, promotes cyst development in ADPKD." (PMID 35847973, 2022). "Interestingly, we found that the treatment of mIMCD3 cells with TNF-α, which has been demonstrated to enhance cyst growth, increased the expression of SMYD3, suggesting a positive feedback loop of SMYD3/TNF-α/NF-κB/SMYD3, in a similar manner to SMYD2." (PMID 38540216, 2024).
liver cancer (6 papers, 2015 to 2023). An epithelial or non-epithelial malignant neoplasm that arises from the liver. "SMYD2 is implicated in the development of breast and liver cancers which have been shown to exhibit gene amplification and/or overexpression of SMYD2." (PMID 26397018, 2015). "High SMYD2 expression in cervical and liver cancer promotes the proliferation of cancer cells and is considered a risk factor for prognosis." (PMID 36816359, 2023). "SMYD2 methylates β-catenin and further promotes its nuclear translocation and activation of Wnt signaling, which is involved the development of liver cancer." (PMID 31548876, 2019). "Since SMYD2 protein is mainly located in the cytoplasm and overexpressed frequently in colorectal and liver cancers where the Wnt/β-catenin pathway is also frequently activated, we aimed to investigate a possible relationship between SMYD2 and β-catenin." (PMID 28915556, 2017). "Breast and liver cancers were identified through in silico data mining as tumor types that display amplification and/or overexpression of SMYD2." (PMID 25825497, 2015).
pancreatic cancer (6 papers, 2016 to 2024). "In pancreatic cancer, SMYD2 was found to be overexpressed, and SMYD2 upregulated the MNAT1 component of CDK-activating kinase (MNAT1), which is a component of cyclin-dependent kinase (CDK)-activating kinase, via H3K36me2 modification in the promoter region." (PMID 39482529, 2024). "SMYD2 has been found to promote RAS-mediated pancreatic cancer formation in in vitro cell and animal studies." (PMID 35432530, 2022). "SMYD2 were highly expressed in pancreatic cancer and knockdown of SMYD2 blocked pancreatic cancer growth by affecting inflammation and stress responses." (PMID 31548876, 2019). "A similar model for SMYD2 has revealed that this enzyme also plays a role in KRAS driven pancreatic cancer initiation and progression and is important for the cellular response to genotoxic agents (e.g. gemcitabine)." (PMID 29856759, 2018). "Together, our findings suggest new roles for SMYD2 in inflammation and stress responses and identify SMYD2 and MAPKAPK3 as potential therapeutic targets to treat pancreatic cancer." (PMID 26988419, 2016). "This SMYD2-mediated MNAT1 upregulation activates the phosphoinositide 3-kinase (PI3K)/AKT serine/threonine kinase (AKT) pathway, leading to increased proliferation of pancreatic cancer cells." (PMID 39482529, 2024). "Moreover, mouse models of KRAS-driven pancreatic cancer were shown to be partially dependent on SMYD2 and indicate that genotoxic agents are more effective in the absence of SMYD2 activity." (PMID 29856759, 2018).
renal fibrosis (6 papers, 2022 to 2025). A final common manifestation of a wide variety of chronic kidney diseases characterized by glomerulosclerosis and tubulointerstitial fibrosis. "Analysis using an experimental model of diabetic nephropathy showed that Ranunculaceae extracts inhibit SMYD2 expression and attenuate renal fibrosis, underscoring the strong association between SMYD2 and metabolism-related disorders." (PMID 39457592, 2024). "Our previous research demonstrated that SMYD2 plays a role in renal fibrosis in the context of unilateral ureteral obstruction, being highly expressed in the kidneys of streptozotocin (STZ)‐induced diabetic mice." (PMID 40391402, 2025). "In a murine model of renal fibrosis, SMYD2 is overexpressed, which induces fibrosis by inhibiting the phosphorylation of profibrotic signaling molecules such as Smad3 and AKT signaling." (PMID 39482529, 2024). "In our previous research, we demonstrated that SMYD2 was highly expressed in STZ-induced renal fibrosis in DN." (PMID 35142600, 2022). "In the kidney, SMYD2 is a key factor in the induction of renal fibrosis." (PMID 39482529, 2024). "This suggests that histone methylation performs a crucial role in promoting fibroblast activation and ECM synthesis, and the occurrence and development of renal fibrosis may be related to the activation of SMYD2." (PMID 35142600, 2022). "Therefore, inhibition of SMYD2 with RTT extract would be a promising therapeutic strategy for the treatment of renal fibrosis." (PMID 35142600, 2022). "The results demonstrate that SMYD2 is a key driver of renal fibrosis, and RTT extract alleviates renal fibrosis by regulating immune regulation and inhibiting SMYD2." (PMID 35142600, 2022).
acute lymphoblastic leukemia (5 papers, 2015 to 2022). Leukemia with an acute onset, characterized by the presence of lymphoblasts in the bone marrow and the peripheral blood. "SMYD2 overexpression promotes disease progression and is correlated with poorer outcomes in childhood acute lymphoblastic leukemia (ALL)." (PMID 34201935, 2021). "Of interest, extracting SMYD2 expression values from the Oncomine cancer array database revealed that SMYD2 levels in AML are lower than in Acute Lymphoblastic Leukemia (ALL)." (PMID 28187429, 2017).
autosomal dominant polycystic kidney disease (5 papers, 2019 to 2022). Autosomal dominant form of polycystic kidney disease. "SMYD2 has been reported to be implicated in the development of cardiovascular disease, cancer, and autosomal dominant polycystic kidney disease (ADPKD)." (PMID 36046818, 2022). "Moreover, Smyd2 regulates autosomal dominant polycystic kidney disease by methylation and activation of STAT3 and p65." (PMID 36270984, 2022). "SMYD2 could directly interact with NF‐κB and enhance its transcriptional activity by methylation of K310 on NF‐κB in the autosomal dominant polycystic kidney disease." (PMID 34841684, 2021). "Given that Smyd2 could methylate and activate the transcription factor STAT3 in autosomal dominant polycystic kidney disease and adipogenesis is intimately linked to STAT3, we were curious whether Smyd2 regulates adipocyte differentiation via activation of STAT3." (PMID 36270984, 2022).
bladder cancer (5 papers, 2016 to 2023). "Interestingly, in addition to Lysine 860, Lysine 810 of RB is also methylated by SMYD2, which enhances Serine 807/811 phosphorylation of RB, and mediates the role of SMYD2 in bladder cancer cell growth." (PMID 31370883, 2019). "Most importantly, the expression level of SMYD2 is significantly increased in human bladder carcinoma compared with nonneoplastic bladder tissues, which indicates that inhibitors of SMYD2 may have a therapeutic effect on bladder carcinoma." (PMID 31370883, 2019). "PKMTs like DOT1L, SMYD2, JMJD2C have been reported in other cancers, but information on PKMTs are generally lacking in bladder cancer." (PMID 28122346, 2017).